EGFR (epidermal growth factor receptor)
Diseases named in the same sentence as EGFR in open-access papers (continued):
Sharing a sentence is not in itself a finding about the gene and the disease.
infection (continued). "Additionally, MuPyV infection of cells resulted in phosphorylation of the epidermal growth factor receptor (EGFR), which was previously shown to be activated during JCPyV entry." (PMID 27803182, 2016). "Changes to EGFR surface levels during infection may reflect functions of pUL135 and pUL138 in altering the internalization or recycling of EGFR-containing vesicles." (PMID 27218650, 2016). "The phosphorylation of the EGFR was also detected early in infection." (PMID 26933809, 2016). "Further work will be important to determine how pUL135 and pUL138 may affect specific phosphorylation sites on EGFR and how these specifically affect EGFR activity in infection." (PMID 27218650, 2016). "To date, several bacterial pathogens have been reported to target EGFR through different mechanisms to facilitate their infection of host cells, including Neisseria gonorrhoeae, Neisseria meningitidis, Helicobacter pylori, Haemophilus influenzae, and Klebsiella pneumoniae." (PMID 27711202, 2016). "EGFR is a major homeostatic regulator controlling cellular proliferation, differentiation, and survival, making it an ideal target for viruses to manipulate during infection." (PMID 27218650, 2016). "Importantly, we found that EGFR modulated SGLT1 expression during infection, but it cannot be concluded unfortunately that the cellular effect of TGEV infection on SGLT1 is mediated via EGFR." (PMID 27851758, 2016). "This evidence confirmed our hypothesis that SS2 infection of hBMEC induced the formation of EGFR/ErbB3 heterodimers." (PMID 27756321, 2016). "The capacity of RSV F to engage EGFR during infection may depend in part on a function of the RSV G protein." (PMID 27152417, 2016). "To determine whether HER3 loss could explain resistance to erlotinib in HCC4006ER cells, we generated Her3 overexpressing cells (HCC4006ER-Her3 cells) using lentiviral infection to examine the effects of erlotinib on cell proliferation and the EGFR pathway." (PMID 26789630, 2016). "Taken together, EGFR signaling mediated infection by RSV expressing the 2–20 F protein." (PMID 27152417, 2016). "Furthermore, when the MMP inhibitor Batimastat was used before SC19 infection, a dose-dependent attenuation of EGFR activation was observed." (PMID 27756321, 2016). "EGFR is a major homeostatic regulator involved in cellular proliferation, differentiation, and survival, making it an ideal target for viral manipulation during infection." (PMID 27218650, 2016). "In addition to its role in regulating surface levels of EGFR in infection, pUL138 has been shown to reduce MRP-1 and enhances TNFR1 levels at the cell surface, although the significance of these changes to latency is not known." (PMID 27218650, 2016). "As EGFR has been shown to facilitate viral entry, this decrease in expression could be a way the host immune system is responding to evade further infection." (PMID 26322025, 2015). "Interestingly, EGFR is activated by H. pylori during early infection, but H. pylori CagA inactivates EGFR during prolonged infection via reducing the phosphorylation of EGFR tyrosine residues." (PMID 26160167, 2015). "Confirmatory data also come from trials with unapproved agents, as these were excluded from both the Qi and Funakoshi analyses, but similar effects have been described, including a 14% rate of infection after therapy with the humanized anti-EGFR-antibody zalutumumab." (PMID 25857245, 2015). "Intriguingly CD4+ and CD8+ T cells showed a significant increase of EGFR expression in the METH exposed LCMV infected group than LCMV alone by 56 days post infection, while a trend of increased expression in the METH treated group was observed at all time-points analyzed." (PMID 26322025, 2015). "We also found another interesting up regulation of epidermal growth factor receptor (EGFR) in METH exposed LCMV infected mice at later times of infection, suggesting that signaling through EGFR may enable to establish persistent infection." (PMID 26322025, 2015).
infection (continued). "The results identify 138 genes associated with the outcome of infection, including the gene encoding the major IMD/REL2 receptor PGRPLC and the epidermal growth factor receptor EGFR, and further suggest that epithelial immune responses against gut bacteria are more complex than previously thought." (PMID 24603764, 2014). "Binding of Grb2 and c-Cbl by EGFR is essential for infection." (PMID 23633955, 2013). "Hence the expression level of EGFR correlates with the level of EB attachment and subsequent infection, indicating that the receptor is involved in mediating infection." (PMID 23633955, 2013). "Finally, recruitment of the adaptor proteins Grb2 and c-Cbl by EGFR is essential for infection by C. pneumoniae." (PMID 23633955, 2013). "When the EGFR was depleted using siRNA, infection decreased only by 50% suggesting that other RTKs may be able to compensate in long-term experiments." (PMID 23593008, 2013). "When the EGFR was depleted using siRNA, greater than 50% reduction in infection was observed." (PMID 23593008, 2013). "Again, the generated recombinant MHVsoR-EGF-His thereby acquired the ability to cause multiround infection of otherwise nonsusceptible, EGFR-expressing cell cultures in vitro, with subsequent efficient cytolytic activity." (PMID 22312365, 2012). "However, in addition to infection mediated by EGFR, the virus retained its capacity to infect cells through binding to the native receptors CAR and integrins." (PMID 22312365, 2012). "Tagging of the proteins with the zipper peptide sequences preserved both the trimerization capability of the adenovirus fiber and the recognition of the EGFR by the zipper-scFv protein, but, most importantly, it gave rise to receptor-specific infection of the target cells." (PMID 22312365, 2012). "Because NTHi infection is mainly characterized by inflammation, it is likely that EGFR may play an important role in mediating NTHi-induced inflammatory response, which is mainly mediated by NF-κB." (PMID 22132240, 2011). "In addition, it was shown that EGFR-mediated Erk-1/2 activation is necessary for the CagA-induced elongation phenotype, which can be suppressed in infection with Hp strains expressing highly active VacA." (PMID 22069547, 2010). "Indeed, preparations of VacA or infection with VacA-expressing Hp exhibited suppressive effects on the phosphorylation and consequently activation of EGFR and HER2/Neu, another member of the EGFR family." (PMID 22069547, 2010). "Altogether, we conclude that the EGFR pathway regulates cell morphogenesis during enterocyte maturation and that this process is critical during normal development of the adult gut, compensatory renewal following infection and aging." (PMID 21176204, 2010). "To further confirm the activation of the EGFR/mitogen-activated protein kinase (MAPK) pathway upon infection, we quantified the levels of phosphorylated (active) forms of the terminal MAPK, ERK, in the gut by immunolocalization with an antibody specific to its phospho-form." (PMID 21176204, 2010). "Reduction of the EGFR pathway in ISCs does not affect the maintenance of ISCs in short term, but prevents their activation in response to damage caused by infection." (PMID 21176204, 2010). "This function of the EGFR pathway in enterocytes is key to maintaining homeostasis, as flies lacking EGFR are highly susceptible to infection." (PMID 21176204, 2010). "Furthermore, our data indicate that activation of the EGFR/MEK pathway is the downstream signalling cascade stimulated by VGF sufficient to elicit a cell survival signal during infection." (PMID 19388902, 2009). "Thus, our results suggest that PilC1 is specifically responsible for the depletion of the EGFR pool in ME180 cells upon infection." (PMID 19718432, 2009). "Furthermore, conditional EGFR knockout was protective during infection." (PMID 41524399, 2026).
infection (continued). "Upon infection with bacteria, EGFR is first phosphorylated at Tyr845, which is phosphorylated by Src kinase, and only then at Tyr1086, which can be phosphorylated in response to the ligand binding of both EGFR itself and integrins that form a complex with EGFR." (PMID 40362195, 2025). "Interestingly, the impact of EGFR inhibition on infected organoids compared to control organoids, is in the same range than overgrowth due to S. Typhimurium, suggesting that enhanced cell proliferation secondary to infection is mainly EGFR-dependent." (PMID 38956132, 2024). "Given the observed heightened reduction in infection among cells treated with SARS-CoV variant pseudoviral particles, including Delta (B.1.617.2), Omicron (BA.2), and Omicron (BA.4/BA.5), 3D spheroids were infected with these variants after blocking the EGFR pathway using osimertinib." (PMID 39291996, 2024). "In conclusion, we demonstrated that in our culture conditions, the infection of caecal organoids with S. Typhimurium recapitulates the main effects on proliferation and differentiation of stem cells and progenitors measured upon in vivo infection, highlighting a major role of the EGFR pathway." (PMID 38956132, 2024). "Thus, we suggest that gB can directly activate EGFR signaling at the early stage of infection." (PMID 37891570, 2023). "In this context it has been suggested that epigenetic inhibitors could be useful to revert this HCV-induced epigenetic signature as well as the EGFR inhibitor erlotinib, for the involvement of the EGFR in the induction of the epigenetic changes following the infection." (PMID 34503196, 2021). "In addition to activating signaling molecules and transcription factors, these functional changes initiated by HCMV gB binding to EGFR serve as a molecular convergence point linking the changes in molecular and biochemical pathways with the biological changes required for productive infection." (PMID 34025614, 2021). "We found that when EGFR was either knocked down with siRNA or inhibited with the specific EGFR kinase inhibitor, gefitinib, C. albicans-induced phosphorylation of EphA2 was transient, occurring within 30 min of infection, but declining to basal levels by 90 min." (PMID 33471869, 2021). "In addition to enhancing the motility, the secreted VGF induces EGFR in a paracrine fashion, which may instruct the neighboring uninfected cells to be metabolically prepared for infection." (PMID 33529218, 2021). "Moreover, the relative infection was increased significantly in the EGFR overexpression group compared to that in the CHO-K1 cell lines or CHO-K1 cells transfected with the control vector (p<0.01), indicating that EGFR plays a major role in early C. psittaci infection." (PMID 35173712, 2021). "Moreover, IAV uptake and subsequent infection are sensitive to EGFR activity inhibition." (PMID 35083168, 2021). "However, EGFR inhibitors will also impair epithelial tissue regrowth necessary to restore respiratory barrier function after severe infections with IAV and other respiratory viruses associated with hyperactive EGFR signaling, such as respiratory syncytial virus (RSV) and SARS-CoV." (PMID 35083168, 2021). "Furthermore, it has been reported that EGFR is activated in response to radiation-induced DNA damage to promote cell survival, and in BoHV-1-infected A549 cells, detectable DNA damage is induced at 24 and 48 hours (h) after infection." (PMID 32846937, 2020).
infection (continued). "HCMV gB engages EGFR and this engagement is also essential for viral entry and productive infection; demonstrating that multiple signaling complexes exist that work in cooperation to drive the biological processes required for productive infection of monocytes/macrophages." (PMID 32850474, 2020). "In order to characterize whether EGFR was activated during infection of A549 cells, protein levels of phospho-EGFR at Tyr1068 (Y1068), a known inducible autophosphorylation site correlated with EGFR kinase activity, was detected via Western blot at 24, 36, and 48 hpi, as determined elsewhere." (PMID 32846937, 2020). "However, there was no detectable difference in the transmigration of CD11b+ and CD11c+ cells into the brain parenchyma and the recruitment of leukocytes into the brain at a time (day 7 post-infection) when T. gondii load was already reduced in Trg-DN EGFR mice." (PMID 30679495, 2019). "However, infection of genetically engineered EGFR(+) CHO cells, resulted in widespread fusion." (PMID 28106842, 2017). "Additionally, pretreatment of epithelial cells with probiotics might extend their ability to restore EGFR signaling after infection with EIEC." (PMID 29682490, 2017). "In conclusion, these data show downregulation of CD9, CD81, CD151, and EGFR upon infection with two herpesviruses, two orthopoxviruses and a negative strand RNA virus, suggesting that the reduction of cell surface expression of these molecules is common upon infection." (PMID 29121670, 2017). "Thus, the use of EGFR-TKIs in NSCLC patients had an increased risk of all-grade infections, but not for high-grade infections." (PMID 28107192, 2017). "During the inflammatory response to injury, EGFR signaling induces expression of toll-like receptors, antimicrobial peptides, cytokines, and chemokines from keratinocytes, contributing to the innate immune response to minimize the potential for infection and promote healing." (PMID 27414801, 2016). "We similarly observed the inverse result after immunoprecipitation with an anti-ErbB3 antibody, showing that EGFR binding was increased upon the phosphorylation of ErbB3, which further strengthened our hypothesis on the formation of EGFR/ErbB3 heterodimers in response to SS2 infection." (PMID 27756321, 2016). "The mechanism of action for this effect has not been established; however, recent studies demonstrating a role for EGFR in regulation of innate immunity suggest that down-regulation of EGFR-dependent signaling in normal tissues may explain an increase in severe infection." (PMID 25857245, 2015). "Therefore, we investigated whether EGFR signalling was affected upon PilC1- or PilC2-mediated infection." (PMID 19718432, 2009). "The Epidermal Growth Factor Receptor (EGFR) and its ligand, amphiregulin (AREG) are critical for epithelial cell proliferation but their important role in inflammation and infection is increasingly described." (PMID 41063987, 2025). "E. tenella microneme protein 4 (EtMIC4), which contains EGF-like domains, can activate host EGFR signaling, thereby regulating downstream Akt and ERK pathway components, suppressing apoptosis, and enhancing infection efficiency." (PMID 41463813, 2025). "We found that HCV-E2 interacted with EGFR after 15 min upon infection, and both HCV-E2 and EGFR transferred from the cell surface into the cell interior (inducing EGFR internalization) by both confocal microscopy and flow cytometry analysis." (PMID 38253527, 2024). "By inhibiting the JNK, JAK-STAT, and EGFR pathways, HEWE or HEBE supplementation contributed to the maintenance of ISC homeostasis in the context of DSS ingestion and Ecc15 infection." (PMID 39543569, 2024). "As a control, we additionally performed infection with VSV-g pseudoviral particles and checked the expression of p-EGFR and EGFR." (PMID 39291996, 2024).
infection (continued). "To further examine the effect of EGFR on PRRSV infection, we examined the viral RNA levels at different time points post-infection in EGFR-knockdown PAMs." (PMID 39469460, 2024). "In instances of corneal epithelial cell damage resulting from trauma, surgery or infection, EGF facilitates the migration and proliferation of corneal epithelial cells through the activation of its receptor EGFR/ErbB and subsequent binding." (PMID 38638937, 2024). "We found that N. meningitidis induces S1P release from brain endothelial cells in parallel with increased expression of S1PR2 and downstream activation of the epidermal growth factor receptor, indicating a shift in the S1PR signalling balance during infection." (PMID 38033162, 2023). "The activation of phosphorylated EGFR is increased during RSV 2-20 infection, and MUC5AC expression is decreased by EGFR inhibitors both in vivo and in vitro." (PMID 38136637, 2023). "Treatment with the Food and Drug Administration-approved, EGFR-specific tyrosine kinase inhibitor, Erlo, resulted in a reduction of HEV p6, 83-2 and enveloped p6 infection events by ~76%, 99%, and 97%, respectively." (PMID 36745934, 2023). "The results demonstrated a gradual 2.1-fold (p-EGFR/β-actin ratio) and 1.7-fold (p-EGFR/EGFR ratio) increase in the expression of phosphorylated EGFR (p-EGFR) protein in RSV-infected cells (MOI 0.1) at 30 and 60 min post-infection." (PMID 38139259, 2023). "Therefore, EGFR downregulation may inhibit an early immunological response to an infection." (PMID 38813031, 2023). "bTregs expressed high levels of CD103, PD-1, EGFR, CTLA-4, Helios, GITR, ST-2, Areg, Ki67, and neuropilin following infection." (PMID 37192971, 2023). "Treatment with a synthetic peptide, SPIKENET (SPK), which inhibits spike protein binding, reduced NGAL mRNA in acute infection, and decreased TGF-β1, BCL3 mRNA, EGFR, HIF1-α, and TLR-2 protein levels long-term post-MHV-1 infection." (PMID 37626956, 2023). "Taken together, our results indicate that phosphorylation and subsequent inactivation of FOXO3a by T. gondii require live infection and occur in a PI3K-AKT-dependent fashion independently of EGFR, PKCα, and mTOR activity in HFF." (PMID 37387601, 2023). "We also found that in immunosuppressed mice, the combined inhibition of EGFR and c-Met ameliorated the severity of OPC, suggesting that strategies to block these host cell receptors hold promise to prevent or treat this infection." (PMID 37611070, 2023). "While treatment with 1 μM JTE-013 greatly prevented infection-induced EGFR phosphorylation, 10 μM JTE-013 reduced EGFR phosphorylation even below activation levels of uninfected control cells." (PMID 38033162, 2023). "By inhibiting the EGFR-MAPK activation, we observe a reduced infection with either spike-pseudotyped particles or authentic SARS-CoV-2, thus indicating that EGFR serves as a cofactor and the activation of EGFR-MAPK contributes to SARS-CoV-2 infection." (PMID 37402592, 2023). "Compared to the mono-infection group, the RNA levels of miR-147 were significantly downregulated, whereas MSI1, KIAA1199, NF-κB p50, and EGFR were significantly upregulated in the bone marrow, livers, and hearts of chickens." (PMID 36291177, 2022). "Apparently, inflammatory cytokines and neutrophil infiltrate levels were dependent on EGFR since both phenotypes in SC5314 and 1052 infection can be reversed by AG1478." (PMID 35720274, 2022). "As expected, the phosphorylations of EGFR, p38 and ERK1/2 at 6 h post-infection were completely inhibited by AG1478, while phosphorylated JNK remained the same level." (PMID 35720274, 2022). "For example, host epidermal growth factor receptor (EGFR) was reported to interact with NTCP and mediate HBV internalization, a finding that potentially accounts for the low rate of infection in the HepG2 cell line, in which EGFR expression is undetectable." (PMID 35495620, 2022).